ZNF488 (zinc finger protein 488)
Description:
Transcriptional repressor. Plays a role in oligodendrocyte differentiation, together with OLIG2. Mediates Notch signaling-activated formation of oligodendrocyte precursors. Promotes differentiation of adult neural stem progenitor cells (NSPCs) into mature oligodendrocytes and contributes to remyelination following nerve injury.
Synonyms: FLJ32104
Tractability: No criterion of Open Targets' tractability assessment is met for any kind of drug.
Gene: Protein-coding gene on chromosome 10 (47,356,520 to 47,384,325, reverse strand). Ensembl gene ENSG00000265763.
Subcellular location: Nucleus
Subcellular location (Human Protein Atlas): Cytosol; Nucleoplasm
Gene Ontology:
Molecular function: protein binding
Biological process: regulation of DNA-templated transcription; positive regulation of myelination; positive regulation of oligodendrocyte differentiation
Cellular component: nucleoplasm; nucleus
Genetic constraint (gnomAD): Loss-of-function variants: 2 observed, 1.87 expected, observed/expected ratio (o/e) 1.07, 90% interval 0.38 to 1.89. That is too few expected variants to judge how well the gene tolerates losing a copy. Missense variants: 450 observed, 455.23 expected, observed/expected ratio (o/e) 0.99, 90% interval 0.91 to 1.07. Synonymous variants: 185 observed, 198.82 expected, observed/expected ratio (o/e) 0.93, 90% interval 0.82 to 1.05.
Homologues: Orthologues: pig ZNF488 (68% identical), dog ZNF488 (64% identical), guinea pig ZNF488 (60% identical), rat Zfp488 (54% identical), mouse Zfp488 (54% identical), zebrafish znf488 (29% identical), Drosophila melanogaster CG13287 (23% identical). Paralogues in human: PRDM8 (31% identical).
Diseases named in the same sentence as ZNF488 in open-access papers:
ZNF488 is named in the same sentence as 6 diseases in open-access papers, as found by Europe PMC text mining. Sharing a sentence is not in itself a finding about the gene and the disease. The quoted sentences say what the papers report.
nasopharyngeal carcinoma (3 papers, 2022 to 2024). A carcinoma arising from the nasopharyngeal epithelium. "Overexpression of ZNF488 contributes to the malignant progression of nasopharyngeal carcinoma and cervical cancer through activating Wnt and MEK/ERK signaling pathway." (PMID 38429817, 2024). "Recently, ZNF488 was reported as an oncogenic protein in nasopharyngeal carcinoma growth and invasion by activation of collagen IV/FAK/AKT/Cyclin D1 pathway and epithelial mesenchymal transition." (PMID 37986084, 2023). "As to ZNF488, overexpression of this protein promotes nasopharyngeal carcinoma (NPC) via induction of collagen IV/FAK/AKT signaling pathway." (PMID 37986084, 2023).
pancreatic cancer (3 papers, 2023 to 2025). "Despite that ZNF488 was also found to be involved in pancreatic cancer cell invasion, the diagnostic potential, biology function and underlying mechanisms of ZNF488 needed further studies to dissect." (PMID 37986084, 2023). "Taken together, SCD1 activation by ZNF488 confers the resistance of pancreatic cancer cells to ferroptosis inducer and ferroptosis-associated chemotherapy." (PMID 37986084, 2023). "However, it remains unknown on the clinical significance, function and underlying mechanisms of zinc finger protein 488 (ZNF488) during the development of pancreatic cancer." (PMID 37986084, 2023). "Study also has reported that overexpression of ZNF488 promotes pancreatic cancer cell proliferation and tumorigenesis by enhancing palmitoleic acid production." (PMID 40376462, 2025). "In summary, we provided the first evidence that ZNF488 contributed to pancreatic cancer tumorigenesis through suppression of ferroptosis which was depending on SCD1-mediated fatty acid metabolism." (PMID 37986084, 2023). "In this study, we observed that ZNF488 overexpression not only suppressed the apoptosis, but also had higher inhibitory effect on the ferroptosis of pancreatic cancer cells." (PMID 37986084, 2023). "The function of ZNF488 in pancreatic cancer was assessed by CCK8, colony formation, EdU staining, PI/Annexin V staining and xenografted tumorigenesis." (PMID 37986084, 2023). "Based on PI/Annexin V and trypan blue staining results, we showed that ZNF488 suppressed the ferroptosis and apoptosis of pancreatic cancer cells." (PMID 37986084, 2023). "Overexpression of ZNF488 contributed to the proliferation and tumorigenesis of pancreatic cancer cells, while opposite effect was observed after ZNF488 knockdown." (PMID 37986084, 2023). "To explore the clinical significance of ZNF488, we compared the expression of ZNF488 in pancreatic cancer and normal tissues." (PMID 37986084, 2023). "In this study, we showed that ZNF488 overexpression conferred poor prognosis of pancreatic cancer patients." (PMID 37986084, 2023). "To explore the function of ZNF488 in pancreatic cancer, we constructed overexpressing and knockdown cells by using lentivirus and siRNAs." (PMID 37986084, 2023). "Rescue experiments demonstrated that ZNF488 overexpression promoted the xenografted tumor development of pancreatic cancer cells, while knockdown of SCD1 largely reversed the phenotype." (PMID 37986084, 2023). "Overexpression of ZNF488 suppresses the ferroptosis and apoptosis to support the growth and tumorigenesis of pancreatic cancer through augmentation of SCD1-mediated unsaturated fatty acid metabolism." (PMID 37986084, 2023). "ZNF488 upregulation suppressed the apoptosis and ferroptosis of pancreatic cancer cells, thus leading to potentiated cancer cell proliferation and growth in vitro and in vivo." (PMID 37986084, 2023). "We found that ZNF488 overexpression promoted, while its knockdown reduced the resistance of pancreatic cancer cells to different concentrations of gemcitabine." (PMID 37986084, 2023). "Taken together, ZNF488 negatively regulates the apoptosis and ferroptosis in pancreatic cancer cells." (PMID 37986084, 2023). "To confirm the effect of ZNF488 on pancreatic cancer cell proliferation, we stained the cells with DAPI and EdU, a predictor for DNA replication and cell proliferation." (PMID 37986084, 2023). "In this study, we revealed that ZNF488 was a worse prognostic factor in pancreatic cancer." (PMID 37986084, 2023). "Thus, ZNF488 overexpression had remarkable significance for the development and clinical treatment of pancreatic cancer patients." (PMID 37986084, 2023). "Furthermore, the overall and disease free survival of pancreatic cancer patients with ZNF488 high expression was significantly shorter than those with ZNF488 low expression." (PMID 37986084, 2023).
pancreatic cancer (continued). "Since ferroptosis and apoptosis play essential role in the cell death induced by gemcitabine, we predicted that ZNF488 expression could regulate the sensitivity of pancreatic cancer cells to the treatment of gemcitabine." (PMID 37986084, 2023). "Combination of SCD1 inhibitors, ferroptosis inducers or gemcitabine could be applied for the treatment of pancreatic cancer with overexpression of ZNF488." (PMID 37986084, 2023). "In this study, we aimed to investigate the clinical significance and biology function of ZNF488 in pancreatic cancer based on TCGA analysis, immunohistochemical staining, gain-of-function, loss-of-function, cell proliferation and xenografted tumorigenesis assays." (PMID 37986084, 2023). "ZNF488 was overexpressed in pancreatic cancer samples compared with normal tissues." (PMID 37986084, 2023). "Collectively, ZNF488 functions as an oncogene in pancreatic cancer." (PMID 37986084, 2023). "Furthermore, ZNF488 overexpression conferred the resistance of pancreatic cancer cells to treatment of gemcitabine, which induced cell death partly through ferroptosis." (PMID 37986084, 2023). "However, the clinical significance, function and molecular mechanisms of ZNF488 in pancreatic cancer development remain less unclear." (PMID 37986084, 2023). "Furthermore, ZNF488 overexpression also promoted the resistance of pancreatic cancer cells to gemcitabine treatment." (PMID 37986084, 2023). "Therefore, ZNF488 contributes to pancreatic cancer development through upregulating SCD1." (PMID 37986084, 2023). "To dissect whether ZNF488 regulates cell death of pancreatic cancer cells, we stained the pancreatic cancer transfected with siCtrl or siZNF488 with PI and Annexin V. Flow cytometry analysis showed that ZNF488 knockdown moderately enhanced the percentage of Annexin V positive cells." (PMID 37986084, 2023). "Our results demonstrate that ZNF488 transcriptional upregulation of SCD1 enhances unsaturated fatty acid production and suppresses fatty acid peroxidation in pancreatic cancer cells." (PMID 37986084, 2023). "To explore the treatment potential of SCD1 axis and ferroptosis for pancreatic cancers with highly expressed ZNF488, we applied SCD1 inhibitors A939572 and erastin to treat pancreatic cancer cells with overexpression of ZNF488." (PMID 37986084, 2023). "Lastly, we investigated the clinical relationship between ZNF488 and SCD1 in pancreatic cancer patients." (PMID 37986084, 2023). "To explore the in vivo role of ZNF488 and SCD1 in pancreatic cancer, we infected the PANC-1 cells with empty Ctrl lentivirus, ZNF488 overexpressing lentivirus and ZNF488 overexpressing with SCD1 knockdown lentivirus." (PMID 37986084, 2023). "Lastly, we found a positive correlation between ZNF488 and SCD1 in pancreatic cancer patients based on TCGA and immunohistochemical staining results." (PMID 37986084, 2023). "The results showed that combination of erastin and SCD1 inhibitors synergistically induced the death of pancreatic cancer cells with highly expressed ZNF488, suggesting that SCD1 inhibitors eliminate the resistance of ZNF488 overexpressed cells to ferroptosis inducers." (PMID 37986084, 2023). "Therefore, ZNF488 upregulation of SCD1 and suppression of ferroptosis could be targeted to enhance the chemotherapy effectiveness of pancreatic cancer patients." (PMID 37986084, 2023).
cervical cancer (2 papers, 2023 to 2024). A primary or metastatic malignant neoplasm involving the cervix. "In cervical cancers, ZNF488 was overexpressed in the patients and it contributed to the malignant growth of the cancer cells via regulating MEK/ERK signaling pathway." (PMID 37986084, 2023).
cancer (2 papers, 2022 to 2023). A tumor composed of atypical neoplastic, often pleomorphic cells that invade other tissues. "To further validate the clinical significance in Chinese patients, we performed immunohistochemical staining of ZNF488 and found that ZNF488 was overexpressed in the cancer tissues." (PMID 37986084, 2023). "Colony formation assay confirmed that ZNF488 knockdown suppressed the growth of cancer cells." (PMID 37986084, 2023). "The results showed that ZNF488 was dramatically upregulated in the cancer tissues." (PMID 37986084, 2023). "We found that ZNF488 was positively correlated with SCD1 in the cancer samples." (PMID 37986084, 2023). "This indicates that ZNF488 or BCL11A increases the stemness of cancer cells." (PMID 35571561, 2022). "TCGA database showed that there was a positive correlation between ZNF488 and SCD1 in the cancer tissues." (PMID 37986084, 2023).
tumor (2 papers, 2022 to 2023). "ZNF488 significantly accelerated the tumor initiation and progression of PANC-1 cells, which were alleviated by SCD1 knockdown." (PMID 37986084, 2023). "However, downregulation of SCD1 could only partly reduce ZNF488-triggered tumor growth, indicating that there might be other molecular mechanisms." (PMID 37986084, 2023). "In addition, we observed that ZNF488 and BCL11A were positively related to the advanced tumor stage and stemness." (PMID 35571561, 2022).
ZNF488 also shares sentences with these, for which no sentence is quoted: neuroendocrine carcinoma (1 paper).